SNORD105 (small nucleolar RNA, C/D box 105)
Synonyms: U105
Gene: Small nucleolar RNA gene on chromosome 19 (10,107,651 to 10,107,735, forward strand). Ensembl gene ENSG00000209645.
Gene Ontology:
Biological process: RNA processing
Cellular component: nucleolus
Homologues: Orthologues: chimpanzee SNORD105 (100% identical), macaque SNORD105 (95% identical), dog SNORD105 (86% identical), pig SNORD105 (84% identical), guinea pig SNORD105 (78% identical), mouse Gm24067 (78% identical), rat Snord105 (76% identical).
Diseases named in the same sentence as SNORD105 in open-access papers:
SNORD105 is named in the same sentence as 1 disease in open-access papers, as found by Europe PMC text mining. Sharing a sentence is not in itself a finding about the gene and the disease.
SNORD105 shares sentences with these, for which no sentence is quoted: leukemia (1 paper).